TSPO (translocator protein)
Diseases named in the same sentence as TSPO in open-access papers (continued):
Sharing a sentence is not in itself a finding about the gene and the disease.
neurodegenerative disease (79 papers, 2014 to 2025). A disorder of the central nervous system characterized by gradual and progressive loss of neural tissue and neurologic function. "The mitochondrial translocator protein (TSPO) is a biomarker of inflammation associated with neurodegenerative diseases, widely regarded to be upregulated in the aging brain." (PMID 40275629, 2025). "The central nervous system (CNS) normally expresses TSPO at low levels, making it notable when there is significant upregulation detected during neuroinflammation associated with dementia and other neurodegenerative diseases." (PMID 37416505, 2023). "TSPO is a major indicator of neuroinflammation and has been implicated in the pathogenesis and progression of many neurodegenerative diseases, including AD." (PMID 36533181, 2022). "As with MS, TSPO PET imaging is widely considered to reflect the pathogenic microglia in neurodegenerative diseases in vivo." (PMID 33433698, 2021). "TSPO is considered to be both a diagnostic biomarker and a therapeutic target for neurodegenerative diseases." (PMID 33708121, 2020). "Translocator protein (TSPO) is a biomarker of neuroinflammation, which is a hallmark of many neurodegenerative diseases and has been exploited as a positron emission tomography (PET) target." (PMID 30900397, 2019). "One of these microglial targets is the 18-kDa translocator protein TSPO, a protein of the outer mitochondrial membrane that is specifically upregulated in activated microglia in injured brain and in neurodegenerative disease associated with neuroinflammation." (PMID 27266706, 2016). "Glial up-regulation of TSPO is a major hallmark of neurodegenerative diseases, and various TSPO ligands have been developed as molecular markers to detect gliosis by means of PET imaging." (PMID 26527153, 2015). "In humans, TSPO ligands are widely used in neuroimaging for neurodegenerative diseases and neuronal injuries, both of which are associated with increased brain TSPO levels and distribution." (PMID 26241038, 2015). "Here, we demonstrate that TSPO deficiency significantly inhibits the phagocytic function of microglia, suggesting that TSPO might be involved in misfolded protein-related neurodegenerative diseases." (PMID 32695005, 2020). "TSPO expression was reported to coincide with the process of microglial activation, which is associated with brain injury and neuroinflammatory conditions such as trauma, neurodegenerative diseases, and neuroinflammatory diseases." (PMID 30034558, 2018). "Unknown factors/problems: However, several practical problems arise with TSPO radiotracers: not distinguishing pro- and anti-inflammatory responses, low signal-to-noise ratio, low variation of dynamic response during neurodegenerative diseases, TSPO polymorphisms." (PMID 33921765, 2021). "On the other hand, TSPO imaging has been performed in a number of autoimmune, infectious, and neurodegenerative diseases, allowing for comparison of relative immune activation across conditions." (PMID 40232849, 2025). "Together, these findings highlight TSPO as a critical regulator of mitochondrial homeostasis, redox balance, and immune function, linking metabolic processes to inflammatory signaling and neurodegenerative disease processes." (PMID 40275629, 2025). "Strict adjustment for sex is required for TSPO-PET studies of microglial activation in human studies of neurodegenerative diseases." (PMID 38263017, 2024). "(R)-11C-PK11195 was the first developed radioligand targeting TSPO, showing disease-related TSPO expression in several neurodegenerative diseases." (PMID 36980337, 2023). "Overexpression of TSPO in active microglia and astrocytes was confirmed to be a reliable indicator of neuroinflammation in other neurodegenerative diseases." (PMID 36890594, 2023). "In vivo human imaging studies have shown that TSPO levels in activated glial cells are increased, especially in neurodegenerative diseases." (PMID 35401924, 2022).
neurodegenerative disease (continued). "TSPO is considered a promising biomarker for neurodegenerative diseases because of the correlation between TSPO overexpression and microglial activation." (PMID 35628296, 2022). "The expression of TSPO was found to significantly increase in microglia and astrocytes during neuroinflammatory and neurodegenerative diseases such as PD." (PMID 35475466, 2022). "Research showed that PF protects astrocytes by participating in the biosynthesis of TSPO and neurosteroids and then plays a therapeutic role in neurodegenerative diseases such as AD." (PMID 35449815, 2022). "There is evidence that translocator protein (18 kDa) (TSPO) expression is upregulated in some neurodegenerative diseases, and TSPO ligands have obvious neuroprotective effects." (PMID 35686060, 2022). "The TSPO expression is increased in neurodegenerative diseases suggesting that TSPO is involved in the development and progression of neurodegenerative diseases." (PMID 35401924, 2022). "This qualifies the cerebellum as a suitable pseudo-reference region for TSPO-PET imaging of neurodegenerative diseases using [18F]GE-180." (PMID 34073557, 2021). "Implications: [18F]F-FETEM can extend our understanding on TSPO implication in neurodegenerative diseases." (PMID 33921765, 2021). "These established findings open a window of opportunity for further investigations of TSPO as a biomarker for astrocyte activation occurring during neurodegenerative diseases." (PMID 32252470, 2020). "The large variability of human TSPO-PET binding in healthy individuals and the allelic dependence of most TSPO tracers predict a need for substantial group sizes to detect sex interactions with TSPO-PET signal in neurodegenerative diseases like AD." (PMID 33317543, 2020). "Strict controlling for sex is required for TSPO-PET studies of microglial activation in mouse models of neurodegenerative diseases and requires attention in corresponding studies in human disease." (PMID 33317543, 2020). "Future studies that examine the longitudinal overlap between astrocytic markers and TSPO expression in neurodegeneration models will inform the extent to which astrocytes contribute to the TSPO PET signal in other neurodegenerative diseases." (PMID 31261683, 2019). "The inflammatory IL-6 level is reportedly increased at 14 months; therefore, TSPO would probably be upregulated at the later stage of brain degeneration." (PMID 31707986, 2019). "The results reported here are particularly relevant for providing novel information on the suitability of [18F] VUIIS1008 for TSPO imaging after neurologic and neurodegenerative diseases." (PMID 29177913, 2017). "Increased TSPO expression has been observed after brain injury and inflammation in neurodegenerative diseases." (PMID 28086916, 2017). "Increased expression of translocator protein (TSPO) has been observed after brain injury and inflammation in neurodegenerative diseases." (PMID 28086916, 2017). "In neurodegenerative diseases and models of neurodegeneration, however, the level of TSPO expression is much lower and more widespread than in focal lesions and is thus more difficult to detect and quantify." (PMID 27481358, 2017). "In future studies, using the “apparently healthy” knockout mouse model, we aim to uncover new features of TSPO that play roles in inflammation and neurodegenerative diseases." (PMID 27907096, 2016). "Over the last few years targets involved in the neuroinflammatory process in neurodegenerative disease other than the TSPO have been identified that are currently evaluated using PET ligands." (PMID 27340650, 2016). "Increased uptake of radioisotope labeled high affinity ligands of TSPO have been used clinically as biomarkers to monitor inflammatory status in neurodegenerative diseases, brain injury and cancer." (PMID 27907096, 2016).
neurodegenerative disease (continued). "In this field, the use of the TSPO PET tracer [18F]DPA-714 in parallel to PET tracers of neurodegeneration would be of great value in rodent models of neurodegenerative disease, as recently done." (PMID 26389120, 2015). "Although TSPO PET is the most widely used biomarker to quantify in vivo central inflammation in patients with neurodegenerative diseases, its signal reflects TSPO overexpression in activated microglia cells and cannot fully capture the complexity of neuroinflammation in these conditions." (PMID 39155063, 2025). "Thus, our data provide evidence of the specificity of the [18F]GE-180 TSPO-PET signal in patients with neurodegenerative diseases." (PMID 37495886, 2023). "The neuroprotective effect of PF on neurodegenerative diseases such as AD may be mediated by TSPO and its downstream neurosteroids." (PMID 35449815, 2022). "In recent years, the development of TSPO-targeted drugs has become a global research hotspot, promising the discovery of new areas in neuropharmacology and facilitating early diagnosis and intervention of neurodegenerative diseases." (PMID 35475466, 2022). "Therefore, it is possible that TSPO affects neurodegenerative diseases by regulating mitochondrial autophagy." (PMID 35401924, 2022). "TSPO is a powerful and precise biomarker of microglial activation in neurodegenerative diseases." (PMID 36278207, 2022). "Under physiological conditions, TSPO expression in the healthy brain is low, while under inflammatory conditions (as they occur during injury or neurodegenerative disease) it is widely upregulated in microglia and astrocytes as well as on the endothelial layer of blood vessels." (PMID 32076115, 2021). "Moreover, in response to neuroinflammation and neurodegenerative diseases, such as PD, the TSPO expression significantly increases in microglia and astrocytes so that TSPO itself has been reported as a marker for microglial activation." (PMID 32933155, 2020). "TSPO is elevated in activated microglia of the CNS but also in astrocytes, endothelial cells, macrophages and monocytes in response to a variety of insults, as well as neurodegenerative diseases." (PMID 31504240, 2019). "Moreover, increased TSPO expression is seen in various neurodegenerative diseases that involve neuroinflammation." (PMID 30704062, 2019). "TSPO is involved in neurodegenerative diseases and psychiatric disorders." (PMID 29506545, 2018). "Indeed, TSPO imaging could provide further information on the role of neuroinflammation in the pathogenesis of PD and neurodegenerative diseases as a whole." (PMID 36980337, 2023). "However, in rat models of axotomy and neuropathy, TSPO ligands improved neural survival and repair, suggesting that TSPO-mediated steroidogenesis could be a potential treatment for neurodegenerative diseases." (PMID 24877623, 2014). "TSPO has been extensively studied as a PET imaging biomarker for neuroinflammation and recently as a target for treating neurodegenerative diseases." (PMID 39919076, 2025). "Neuroinflammation is a feature of many neurodegenerative diseases and is quantified in vivo by PET imaging with radioligands for the translocator protein (TSPO, e.g. 11C-PK11195)." (PMID 40036275, 2025). "TSPO PET imaging is widely used to monitor inflammation in MS, a chronic inflammatory demyelinating and neurodegenerative disease with onset in young adults." (PMID 33433698, 2021). "Sex-specific effects on the age-dependent increase in cortical TSPO-PET signal are present in wild-type mice and in mouse models of neurodegenerative diseases." (PMID 33317543, 2020). "TSPO PET imaging has been employed as a neuroinflammatory biomarker mainly in the assessment of microglial activity in neurodegenerative diseases rather than in musculoskeletal pain conditions." (PMID 40918986, 2025).
neurodegenerative disease (continued). "No studies have been conducted to investigate the TSPO expression at the cellular level in other neurodegenerative diseases such as ALS, Huntington’s disease, or spinocerebellar atrophy." (PMID 33433698, 2021). "Evidence for involvement of microglia in neurodegenerative diseases is supported by the post mortem assessment of human brain tissue, animal models, and by positron emission tomography (PET) studies with radiolabeled translocator protein (TSPO) ligands in patients." (PMID 26813748, 2016). "11C-PK-11195, which binds to the translocator protein (TSPO) that is expressed on the outer mitochondrial membrane of activated microglia, is a robust and sensitive marker of microglial activation with an established role as a proxy for neuroinflammation in neurodegenerative diseases." (PMID 32179883, 2020). "Moreover, as described in the previous paragraphs, neuronal TSPO seems to play little or no role in neurodegenerative diseases." (PMID 32839410, 2020). "In addition, due to the proposed function of TSPO in apoptosis, potentially via its interactions with VDAC1, interfering with the TSPO-VDAC1 interaction can offer a target for the development of drugs directed at neurodegenerative diseases." (PMID 31288390, 2019). "However, TSPO is distributed throughout the entire brain, even at very low density, and no clear reference region may exist in neurodegenerative diseases." (PMID 28398245, 2017).
psychiatric disorder (38 papers, 2011 to 2026). A disorder characterized by behavioral and/or psychological abnormalities, often accompanied by physical symptoms. "The presence of this TSPO polymorphism has been linked to the function of the hypothalamic-pituitary-adrenal axis, predisposing carriers to psychiatric disorders, and potentially impairing the response of patients to anxiolytic TSPO drug ligands." (PMID 33433698, 2021). "Crystal structures of TSPO (at resolutions of 1.8, 2.4, and 2.5 angstroms) from a mutant that mimics the human Ala147Thr polymorphism associated with psychiatric disorders and reduced cholesterol metabolism was determined." (PMID 31288390, 2019). "The association between TSPO expression in glial cell types involved in neuroinflammation enables the use of TSPO-specific ligand measurements to assess the presence and degree of neuroinflammation in neurological and psychiatric disease." (PMID 33515765, 2021). "However, the presence of rs6971 polymorphism (A147T) on the TSPO gene can affect the hypothalamic–pituitary–adrenal axis, predisposing carriers to psychiatric disorders." (PMID 32961709, 2020). "Indeed, there is evidence that the dysregulation of steroidogenesis by TSPO is associated with psychiatric disorders." (PMID 28387722, 2017). "As the prototypical first-generation TSPO radioligand, 1 was widely employed for decades in imaging TSPO in neurological and psychiatric disorders." (PMID 39275061, 2024). "Mitochondrial lipid translocator protein Tps0 (SPBC725.10) is a homologue of human TSPO, which is thought to be a molecular sensor of brain injury and repair and is considered a therapeutic target for neurological and psychiatric disorders." (PMID 37859837, 2023). "TSPO has been suggested as potential endophenotype and therapeutic target for psychiatric disorders, and can be imaged in vivo using positron emission tomography imaging (PET)." (PMID 32076115, 2021). "Several PET studies of TSPO as a marker of inflammation in psychiatric disorders have been performed but with differing outcomes." (PMID 33433698, 2021). "Recent emerging evidence strongly supports the use of TSPO as a neuroimmunomodulatory target to detect neuroinflammation in neurological and psychiatric disorders." (PMID 31901235, 2020). "PET imaging of TSPO is widely used to monitor neuroinflammation in neurological and psychiatric disorders." (PMID 32198578, 2020). "In previous studies, several TSPO agonists were found to be valuable and effective for the in vivo treatment of a wide range of neurological and psychiatric disorders, including pain." (PMID 29770147, 2018). "Apart from epidemiological and genetic evidences of overlap between BD and schizophrenia (SCZ), molecular imaging of microglia of these psychiatric disorders also share some similarities, especially hippocampal TSPO overexpression compared to normal controls." (PMID 28387722, 2017). "Evidence indicates that neuroinflammation may play a role in psychiatric disorders, most often studied through imaging of the mitochondrial protein TSPO found in glial cells." (PMID 39576337, 2025). "TSPO can be elevated in mental disorders, such as major depression." (PMID 40732235, 2025). "The fact that TSPO loss impaired cellular energy metabolism, as evidenced by altered Ca2+ homeostasis, reduced OXPHOS, and depolarisation of MMP, is in favour of the hypothesis that TSPO might be a promising target for the treatment of psychiatric disorders." (PMID 39684592, 2024). "Due to the prolific research into TSPO binding agents, several reviews have covered the many TSPO molecular imaging agents and their use in imaging studies in a spectrum of disorders, including neurodegenerative disorders, psychiatric disorders and tumours." (PMID 32102369, 2020).
psychiatric disorder (continued). "From the descriptions and discussions above, it appears that in association with inflammatory responses, including microglial activation, enhanced TSPO levels accompany neuropathologies that occur in the brains of people suffering from neurodegeneration and psychiatric disorders." (PMID 32252470, 2020). "Changes in TSPO expression have also been detected in psychiatric disorders." (PMID 31288390, 2019). "Moreover, TSPO is involved in regulating cellular downstream processes such as proliferation, survival, and apoptosis and plays multiple roles in health and disease, ranging from neurodegeneration and neoplasia to psychiatric disorders." (PMID 39684592, 2024). "However, psychiatric disorders are more heterogeneous in neuropathology and several factors may affect the reproducibility of results and retard the broad use of TSPO-PET at present." (PMID 36624089, 2023). "Thus, it appears worthwhile to investigate TSPO’s involvement in psychiatric disorders." (PMID 32252470, 2020). "Evaluation of translocator protein (TSPO) overexpression is considered an attractive research tool for monitoring neuroinflammation in several neurological and psychiatric disorders." (PMID 25771904, 2015). "Additionally, the potential effects of inflammation on psychiatric disorders and pharmacological interventions have also been explored using PET radiotracers targeting the translocator protein (TSPO) as a marker for activated microglia." (PMID 41159681, 2026).